WFDC8 (WAP four-disulfide core domain 8)
Synonyms: C20orf170; WAP8; dJ461P17.1; HEL-S-292
Tractability: Antibody: UniProt places it where antibodies can reach, with high confidence; UniProt predicts a signal peptide or a membrane-spanning region; its Gene Ontology location is reachable by antibodies, with medium confidence.
Gene: Protein-coding gene on chromosome 20 (45,551,153 to 45,579,326, reverse strand). Ensembl gene ENSG00000158901.
Subcellular location: Secreted
Gene Ontology:
Molecular function: peptidase inhibitor activity; serine-type endopeptidase inhibitor activity
Cellular component: extracellular region
Genetic constraint (gnomAD): Loss-of-function variants: 23 observed, 27.11 expected, observed/expected ratio (o/e) 0.85, 90% interval 0.61 to 1.2. The upper end of that interval is the gene's LOEUF score, 1.2, which puts it in group 5 of 6, group 1 being the genes least tolerant of losing a copy. Missense variants: 226 observed, 252.62 expected, observed/expected ratio (o/e) 0.89, 90% interval 0.8 to 1. Synonymous variants: 86 observed, 85.6 expected, observed/expected ratio (o/e) 1, 90% interval 0.84 to 1.2.
Homologues: Orthologues: chimpanzee WFDC8 (98% identical), macaque WFDC8 (86% identical), dog WFDC8 (61% identical), rabbit WFDC8 (58% identical), pig WFDC8 (56% identical), mouse Wfdc8 (50% identical), rat Wfdc8 (45% identical), zebrafish spint1a (21% identical), zebrafish spint1b (20% identical), zebrafish wfikkn1 (17% identical), Caenorhabditis elegans C02F12.5 (13% identical), Caenorhabditis elegans Y55F3BR.2 (12% identical), and 5 more. Paralogues in human: SPINT1 (22% identical), WFIKKN2 (21% identical), WFIKKN1 (20% identical), AMBP (18% identical), TFPI (17% identical), TFPI2 (17% identical), KIAA0319L (16% identical), SPINT2 (15% identical), KIAA0319 (13% identical), EPPIN (11% identical), LRP11 (11% identical), SPINT4 (9% identical), and 1 more.
Diseases named in the same sentence as WFDC8 in open-access papers:
WFDC8 is named in the same sentence as 3 diseases in open-access papers, as found by Europe PMC text mining. Sharing a sentence is not in itself a finding about the gene and the disease. The quoted sentences say what the papers report.
colon cancer (1 paper, 2012). "Therefore, because of the known cancer and disease relevance of mutations in the WAP domain of other genes, the presence of mutations in the WAP domain of WFDC8 encourage further study of the role of WFDC8 in colon cancer development." (PMID 22759657, 2012).
lung carcinoma (1 paper, 2012).
WFDC8 also shares sentences with these, for which no sentence is quoted: cancer (1 paper).